SNHG12 (small nucleolar RNA host gene 12)
Diseases named in the same sentence as SNHG12 in open-access papers (continued):
Sharing a sentence is not in itself a finding about the gene and the disease.
liver fibrosis (1 paper, 2024). "Snhg12 has been identified to be an underlying target for treating liver fibrosis." (PMID 38946724, 2024). "Snhg12 has been identified as an underlying target for treating liver fibrosis." (PMID 38946724, 2024). "Herein, Snhg12 expression was shown to be increased within mouse liver fibrosis tissue samples, and the knockdown of Snhg12 impeded the progression of liver fibrosis." (PMID 38946724, 2024). "Herein, SNHG12 expression was shown to be increased within human liver fibrosis tissue samples by bioinformatics analysis." (PMID 38946724, 2024). "Given that lncRNA Snhg12 expression showed to be increased within liver fibrotic tissue samples, lncRNA Snhg12 knockdown subsequently explored its function in a liver fibrosis mouse model." (PMID 38946724, 2024). "Herein, the function and related mechanisms of lncRNA Snhg12 within hepatic fibrosis were investigated." (PMID 38946724, 2024). "In this study, the expression level of Igfbp3 was shown to be increased within mouse liver fibrosis tissues by bioinformatics analysis and positively correlated with Snhg12 expression." (PMID 38946724, 2024). "In conclusion, the proliferation and activation of mHSCs were markedly reduced by knocking down Snhg12, a lncRNA that was abnormally overexpressed in liver fibrosis." (PMID 38946724, 2024). "In conclusion, LncRNA Snhg12 mediates liver fibrosis by targeting IGFBP3 and promoting its protein stability, thereby promoting mHSC proliferation and activation." (PMID 38946724, 2024). "Herein, lncRNA Snhg12 exhibited abnormally high expression within mouse liver fibrotic tissue samples and TGF‐β1‐treated mHSCs, and the knockdown of Snhg12 retarded the development of liver fibrosis in mice by suppressing HSC proliferation and activation." (PMID 38946724, 2024). "LncRNA Snhg12 is expected to be a potential target for the treatment of liver fibrosis." (PMID 38946724, 2024). "CCl4‐treated liver fibrosis mice were infected with Lv‐sh‐Snhg12#1 and Lv‐sh‐Snhg12#2 knockdown lentiviruses, as confirmed by qRT‐PCR, revealing that Snhg12 knockdown lentiviruses significantly reduced Snhg12 expression within the mouse liver tissues." (PMID 38946724, 2024). "Notably, lncRNA Snhg12 and Igfbp3 expression levels exhibited a positive correlation within human and mouse liver fibrosis expression datasets (GSE84044, GSE123932, and GSE207857)." (PMID 38946724, 2024). "Since there are no reports on the association of SNHG12 with liver fibrosis, their function and mechanism in liver fibrosis need to be elucidated." (PMID 38946724, 2024). "“lnc Snhg12/IGFBP3 axis promote liver fibrosis by promoting HSC proliferation and activation”." (PMID 38946724, 2024). "In summary, this study underlines for the first time that lncRNA Snhg12 expression is increased within liver fibrosis tissues of mice, and the Snhg12/IGFBP3 axis could promote liver fibrosis by promoting HSC proliferation and activation." (PMID 38946724, 2024). "Taken together, lncRNA Snhg12 can promote TGF‐β1‐induced mHSCs proliferation and activation and subsequently advances the liver fibrosis process by up‐regulating IGFBP3 expression." (PMID 38946724, 2024). "Given that the expression of lncRNA Snhg12 was increased within mouse liver fibrosis tissue samples and TGF‐β1‐induced mHSC cell models, the function of Snhg12 in mHSCs proliferation and activation was investigated by knocking down lncRNA Snhg12." (PMID 38946724, 2024). "In contrast, overexpression of Snhg12 could boost HSC proliferation and activation and exacerbate liver fibrosis by up‐regulating IGFBP3 expression." (PMID 38946724, 2024).
neuropathic pain (1 paper, 2022). Chronic pain caused by damage to nerve fibers. "In this study, results suggest that lncRNA SNHG12 expression is significantly increased in DRGs from rats with SNI; thereafter, we hypothesised that lncRNA SNHG12 participates in the initiation or progression of SNI-induced neuropathic pain." (PMID 35624111, 2022).
prostate adenocarcinoma (1 paper, 2020). "SNHG12 and cyclin E1 (CCNE1) expression levels were also positively correlated in prostate adenocarcinoma (PRAD)." (PMID 33294456, 2020).
psoriasis (1 paper, 2023). An autoimmune condition characterized by red, well-delineated plaques with silvery scales that are usually on the extensor surfaces and scalp. "We also corroborated the involvement of eight lncRNA genes involved in psoriasis as determined by previous studies, including EPHA1-AS1, CYP4Z2P, SNHG12, LINC01215, LINC1206, SH3PXD2A-AS1 and CERNA2." (PMID 38003532, 2023).
pulmonary hypertension (1 paper, 2021). Increased pressure within the pulmonary circulation due to lung or heart disorder. "Then, we further assessed the expression of CCR7, let‐7e‐5p and SNHG12 in the Su/Hx‐induced pulmonary hypertension mouse model." (PMID 33630421, 2021).
renal carcinoma (1 paper, 2019). A carcinoma arising from the epithelium of the renal parenchyma or the renal pelvis. "Our previous results demonstrated that over-expression of SNHG12 was prevalent in renal carcinoma, which intimately associated with poor outcomes." (PMID 31114448, 2019). "Noteworthily, the molecular mechanism underlying high-expression of SNHG12 in renal carcinoma was still to be elucidated in our future investigations." (PMID 31114448, 2019). "Consistent with results from transwell assay, the wound healing speed was decelerated in SNHG12-deficient cells compared to the proficient ones, which highlighted the critical role of SNHG12 in promotion of renal cancer cell migration." (PMID 31114448, 2019). "Our study for the first time highlighted the critical role of SNHG12-miR-199a-5p-HIF1α axis underlying the malignant features of renal carcinoma." (PMID 31114448, 2019). "High expression of SNHG12 significantly associated with poor prognosis in renal cancer patients." (PMID 31114448, 2019). "Moreover, SNHG12-deficiency compromised both migrative and invasive capacity in renal cancer in vitro as well." (PMID 31114448, 2019). "Our data clearly elucidated that miR-199a-5p predominately antagonized the oncogenic feature of SNHG12 in renal cancer." (PMID 31114448, 2019). "Here we attempted to analyze the relative expression of SNHG12 and address its mechanistic relation to renal cancer." (PMID 31114448, 2019). "We characterize aberrant over-expression of SNHG12 in renal carcinoma, which competed with miR-199a-5p to positively regulate HIF1α." (PMID 31114448, 2019). "Mechanistically, we elucidated that SNHG12 functioned as competing endogenous lncRNA against miR-199a-5p, and SNHG12 inversely correlated to endogenous miR-199a-5p in renal carcinomas." (PMID 31114448, 2019). "Our results clearly showed that impairment of SNHG12 significantly inhibited viability, anchorage-independent growth and induced cell apoptosis in renal carcinoma cell lines." (PMID 31114448, 2019). "Consistently, in this study, we first characterized aberrant overexpression of SNHG12 in renal carcinoma both in vivo and in vitro." (PMID 31114448, 2019). "Here we consolidated the phenotype in renal carcinoma xenograft tumor and validated the oncogenic activity of SNHG12 in vivo." (PMID 31114448, 2019). "In agreement with several previous studies into solid tumors, our data acquired both in vivo and in vitro showed the universal overexpression of SNHG12 in renal carcinoma." (PMID 31114448, 2019). "Then, we sought to evaluate the oncogenic properties of SNHG12 in renal cancer along this direction." (PMID 31114448, 2019). "In summary, our data provided evidences that SNHG12 played important roles in promotion of renal cancer metastasis during disease progression." (PMID 31114448, 2019). "The previous study indicated that SNHG12 was subjected to the regulation by the transcription factor C-Myc, which was frequently over-activated in renal carcinoma." (PMID 31114448, 2019). "However, the expression status and potential involvement of SNHG12 in renal cancer has not been fully understood." (PMID 31114448, 2019). "Notably, the negative correlation between miR-199a-5p and HIF1α and positive correlation between SNHG12 and HIF1α have been characterized in renal cancer patients." (PMID 31114448, 2019). "Consistent with previous study that suggested miR-199a-5p negatively and post-transcriptionally regulated HIF1α in brain tissue of patients with intractable epilepsy, here we consolidated this regulatory axis in renal carcinoma which was further subjected to SNHG12 competition." (PMID 31114448, 2019). "We further quantified SNHG12 expression in our available renal cancer cell lines regardless of the mutation status of VHL." (PMID 31114448, 2019). "SNHG12 was aberrantly up-regulated in renal carcinoma both in vivo and in vitro." (PMID 31114448, 2019). "Our data uncovered a crucial role of SNHG12-miR-199a-5p-HIF1α axis in human renal cancer." (PMID 31114448, 2019).
renal carcinoma (continued). "In summary, here we identified the oncogenic property of SNHG12 via miR-199a-5p-HIF1α pathway, which contributed to our comprehensive understanding of the hypoxia response in VHL-proficient renal carcinoma." (PMID 31114448, 2019).
tumor (80 papers, 2017 to 2025). "In a subset of tumors, high expression of RCC1/SNHG3/SNHG12 caused enhanced mitotic and DNA damage repair processes in tumor cells, thereby enhancing cell viability and promoting cell proliferation." (PMID 36148010, 2022). "Next, we analyzed the tumor mutation landscape of RCC1/SNHG3/SNHG12 expression in KICH using the SangerBox tool." (PMID 36148010, 2022). "An existing study determined an elevated SNHG12 expression in GC tissues with an underlying correlation between the SNHG12 overexpression and the severity of tumor invasion and poor survival." (PMID 35383161, 2022). "To further clarify the molecular mechanisms of SNHG12 in GC proliferation, we investigated the relationship between SNHG12 and HuR, an established tumor-associated RBP." (PMID 34195070, 2021). "The higher expression level of SNHG12 was also linked with higher tumour grade and indicated a worse prognosis." (PMID 32641718, 2020). "We also found that higher expression of SNHG12 was associated with a greater tumor invasion depth and poorer survival in GC patients." (PMID 31808752, 2019). "The xenograft tumor progression was significantly inhibited by SNHG12 knockdown, with the average weight of tumor was 0.53 ± 0.09 g in SNHG12-deficient recipients versus 1.33 ± 0.05 g in control group." (PMID 31114448, 2019). "The lncRNA small nucleolar RNA host gene 12 (SNHG12) has been revealed to play a carcinogenic role in various neoplasms, but the underlying mechanism in ccRCC is still unclear." (PMID 31824846, 2019). "Moreover, presence of lymph node metastasis and larger tumor size were statistically linked to SNHG12 overexpression (p < 0.05)." (PMID 37795578, 2023). "Additionally, SNHG12 was strikingly elevated in GC, and its expression was closely linked with the tumor size, tumor lymph node metastasis stage, distant metastasis, and lymphatic metastasis." (PMID 35383161, 2022). "There have been many speculations about the mechanisms underlying the regulation of tumor progression by SNHG12." (PMID 33994849, 2021). "SNHG12 was expressed at a higher level in tumour tissues than in normal tissues, and the receiver operating characteristic (ROC) curve showed that SNHG12 could be used as a diagnostic biomarker for ccRCC." (PMID 32641718, 2020). "Moreover, SNHG12 abundance was found to be associated with increased metastasis, high-grade tumor (stage III-IV), low overall survival rate, and poor prognosis." (PMID 31620362, 2019). "Moreover, SNHG12 abundance was associated with various clinical parameters, including advanced tumor grade, tumor size, lymph node metastasis, and Enneking staging, while its over-expression was negatively associated with overall survival rate." (PMID 31620362, 2019). "Furthermore, the aggregated data showed that SNHG12 high expression was associated with tumor stage (P < 0.00001), poor cancer outcome (P = 0.01), positive lymph node metastases (P < 0.00001), distant metastases (P = 0.0006), and tumor size (P < 0.00001)." (PMID 34372942, 2021). "We then used data from The Cancer Genome Atlas to assess the association of SNHG12 expression with the clinicopathological characteristics and prognosis of GC patients and found that higher SNHG12 expression was associated with a greater tumor invasion depth and poorer survival." (PMID 31808752, 2019). "Collectively, these findings suggested that SNHG12-mediated SLC7A11 upregulation promoted the adaptation of NSCLC cells to TAM2 polarization in the tumor microenvironment." (PMID 40417819, 2025). "SNHG6 was expressed at the tumor edge and in the pseudopalisading regions around necrosis, but most lncRNAs (Pvt1, SNHG12, H19, Neat1, Malat1, Mir17hg and Ftx) were expressed around the necrotic tumor regions." (PMID 40527978, 2025). "Results of the present study demonstrated that SNHG12 knockdown significantly decreased tumor size, volume and weight." (PMID 40417819, 2025).
tumor (continued). "Collectively, these results demonstrated that exosomal SNHG12 had a promotive effect on angiogenesis and tumor growth." (PMID 38833118, 2024). "According to the 2021 review, anoikis-related lncRNAs including ANRIL, FOXD2-AS1, HOTAIR, and SNHG12 have been unveiled to participate in the process of tumor metastasis, stem cell formation and tumor survival." (PMID 38385949, 2024). "In vivo studies further confirm our findings that SNHG12-deleted exosomes inhibited tumor progression and reduced MVD." (PMID 38833118, 2024). "The results suggest that RCC1/SNHG3/SNHG12 are involved in the immune infiltration process to some extent and play an important role in immune-tumor interactions." (PMID 36148010, 2022). "SNHG12 expression is upregulated in RCC tumor tissues while its knockdown markedly inhibits RCC cell viability and invasion, while increasing apoptosis." (PMID 35597996, 2022). "The strong tumor correlation shown by RCC1/SNHG3/SNHG12, especially RCC1, in tumor diseases deserves further investigation." (PMID 36148010, 2022). "SNHG12 was involved in unfolded protein responses in many tumor cells, which were exploited to evade the immune-mediated attack and correlated with chemotherapeutic or targeted drug resistance in various malignancies." (PMID 35592674, 2022). "Inhibition of SNHG12 repressed PCa cell proliferation, invasion, migration and promoted apoptosis and autophagy in vitro, as well as suppressing tumour growth in vivo." (PMID 35159022, 2022). "In our data, SNHG12 was downregulated in the EP subtype hinting at a possible dual role as both oncogene and tumor suppressor which needs to be further investigated." (PMID 36386805, 2022). "While much work has been performed on SNHG12 and its dysregulation in multiple cancer cell lines and tumor samples, little is known about its function in the vasculature." (PMID 34793334, 2022). "Results suggested that SNHG12 knockdown significantly suppressed the xenograft tumour growth, whereas inhibition of miR‐30a‐3p rescued the xenograft tumour growth comparing with the group treated with SNHG12‐KD cells and vehicle control." (PMID 33787057, 2021). "Next, we analysed the expression of SNHG12 in ccRCC tumour tissues based on the data from The Cancer Genome Atlas (TCGA) database using ENCORI software." (PMID 33787057, 2021). "In tumors, SNHG12, which is an oncogene, promotes the process of tumor formation through the cell cycle, invasion, metastasis, and apoptosis." (PMID 34372942, 2021). "First, we measured the expression of SNHG12 in 90 pairs of ccRCC tumour samples and adjacent normal renal tissue samples by qRT‐PCR." (PMID 33787057, 2021). "The results were consistent with our findings that SNHG12 is significantly up‐regulated in ccRCC tumours (n = 523) compared with normal renal tissues (n = 100)." (PMID 33787057, 2021). "Our data also suggested that knockdown of SNHG12 in ccRCC cells significantly repressed in vivo tumour growth, whereas knockdown of miR‐30a‐3p partially rescued the in vivo tumour growth." (PMID 33787057, 2021). "To identify the functional lncRNA in ICC progression, we searched TCGA datasets and focused on SNHG12 which was distinctly overexpressed in ICC specimens (n = 36) compared with non-tumor specimens (n = 9)." (PMID 34239888, 2021). "The results of tumor transplantation in nude mice showed that tumor weight and volume were markedly increased after overexpression of SNHG12 and the positive rate of Ki67 protein was also increased." (PMID 34656115, 2021). "In the TCGA database, abnormally high expression of SNHG12 in tumor samples indicates that the patient has a poor prognosis." (PMID 34372942, 2021). "In vivo experiments also showed that knockdown of SNHG12 significantly inhibited xenograft tumour growth, and co‐silencing of SNHG12 and miR‐30a‐3p partially compromised the tumour growth." (PMID 33787057, 2021). "SNHG12 is a dysregulated molecule in the pathogenesis, progression and prognosis of diverse neoplasms." (PMID 33968736, 2021).